IL10 (interleukin 10)
Diseases named in the same sentence as IL10 in open-access papers (continued):
Sharing a sentence is not in itself a finding about the gene and the disease.
Chronic colitis (continued). "Increased IL-10 expression was noted in the colonic tissues of mice at the stages of acute and chronic colitis, which we believe could be partly responsible for the anti-inflammatory activity of embelin." (PMID 26799669, 2016). "The Breg subset characterized by increased CD1d expression was first identified in a mice model of chronic colitis in which CD1dhi B cells produced IL-10 and suppressed the progression of intestinal inflammation through the repression of IL-1 and STAT3 activation in a CD1d-dependent manner." (PMID 24019869, 2013). "One key feature of the novel infection model presented here is the very early beginning of antibiotic treatment in IL-10−/− mice: Eradicating any commensal bacteria right after weaning abolished the main trigger for inducing and perpetuating chronic colitis in IL-10−/− animals." (PMID 22808254, 2012). "Therefore, it can be speculated that IL-10-mediated DC may be the main reason why WGP inhibits chronic colitis." (PMID 36713833, 2023). "Butyrate also promotes IL-10 production from intestinal epithelial cells in a GPR109a-dependent manner, indicating that the preventive effect of AX on chronic colitis may be explained by the butyrate-dependent functional modification of the colonic tissue cells." (PMID 37049841, 2023). "In IL-10 gene knock-out animals, the absence of this molecule led to uninterrupted activation of the inflammasome, due to the constant stimulation of microorganisms, causing chronic colitis." (PMID 34630405, 2021). "In conclusion, deficiency of IL-33 does not alter the severity of chronic colitis in Il10−/− mice." (PMID 33953267, 2021). "Regardless of whether there was anti-CD3/CD28 antibody stimulation, IFN-γ, IL-17A, and IL-21 were significantly decreased (P < 0.05), and IL-10 was significantly increased in the chronic colitis + Se-enriched L. acidophilus group compared with the chronic colitis group (P < 0.05)." (PMID 34532332, 2021). "In addition, it could ameliorate Th1-mediated chronic colitis and disordered immune state in IL-10(−/−) mice by inhibiting TNF-alpha/TNFR2 signal pathway." (PMID 32293395, 2020). "Hence, C. coli accelerates inflammatory immune responses in IL-10-/- mice with chronic colitis." (PMID 32664563, 2020). "Similarly to previous reports, progression from acute to chronic colitis in wt mice was associated with a reduced expression of IFNγ and IL-6, accompanied by an increased (albeit not significant) IL-10 levels." (PMID 20706593, 2010). "In IL-10 knockout (IL10−/−) mice, the GDNP treatment showed anti-inflammatory activity that was able to prevent chronic colitis." (PMID 39195369, 2024). "The concentrations of IFN-γ, IL-21, and IL-17A were significantly lower, while the concentration of IL-10 was significantly higher, in the NAM+chronic colitis group than in the chronic colitis group." (PMID 33748287, 2021). "The intervention of TFA increased the levels of IL-10 and TGF-β, and downregulated the expression of pro-inflammatory factors IL-17, IL-6, TNF-α, and IFN-γ in TNBS-induced chronic colitis." (PMID 35002710, 2021). "SJMHE1 treatment decreased the expression of IL-17A mRNA and increased the expression of IL-10 mRNA in the splenocytes and colon compared with the respective expression levels in the DSS- and/or DSS/PBS-treated mice with chronic colitis." (PMID 34488863, 2021). "In conclusion, TOE is effective in preventing chronic colitis through the upregulation of FOXP3+ Treg cells and its secreted anti-inflammatory cytokine, IL-10." (PMID 33092149, 2020). "Conversely, activated Tregs inhibit Th17 cell the differentiation via secretion of IL-10 and TGF-β, which results in attenuation of chronic colitis." (PMID 29760423, 2018). "In a chronic colitis model resembling human IBD, we also found that IL-10 inhibited inflammasome/IL-1 pathway, and the pathogenicity of Th17 cells, leading to reduced chronic intestinal inflammation." (PMID 27308096, 2016).
Chronic colitis (continued). "We evaluated the effects of treatment with low doses of interleukin 10 and anti-IL1 antibody on intestinal permeability in the model of chronic colitis by means of Ussing Chamber apparatus." (PMID 27785242, 2013). "In addition, the effect of EVs was evaluated in adult C57BL/6 mice treated with DSS and adult IL-10−/− C57BL/6 mice treated with piroxicam, which were used as acute and chronic colitis models, respectively." (PMID 39595633, 2024). "Moreover, compared to L. lactis and L. lactis producing IL-10, it exerted a greater ability to alleviate chronic colitis induced by DSS and IL-10−/−." (PMID 37049407, 2023). "It is worth noting that our results revealed an increase in the levels of IL-10 and IL-4 in non-treated chronic colitis rats." (PMID 37513865, 2023). "Indeed, a recent study reported that animals with chronic colitis had a parallel increase in the cytokine levels of TNF-alpha, IL-1-beta, IL-6 and IL-10 in their blood and hippocampus." (PMID 35269413, 2022). "Collectively this data does not support a role for IL-33 in regulating spontaneous chronic colitis in Il10−/− mice." (PMID 33953267, 2021). "Four weeks following C. coli infection, IL-10-/- mice with chronic colitis did neither display more frequent nor more severe clinical signs of intestinal inflammation as compared to mock-infected counterparts." (PMID 32664563, 2020). "We explored the use of piroxicam, EtOH, TNBS, and DSS with various dosage regimens for inducing/enhancing chronic colitis in both IL-10-/- and FVB mice, and monitored the chronic colitis with dual-selectin targeted USMI by using clinical and small animal US scanners." (PMID 31534535, 2019). "Converse to wildtype counterparts, Psae colonized the intestines of IL-10−/− mice with chronic colitis following peroral challenge, but did not lead to changes in intestinal microbiota composition." (PMID 29704005, 2018). "For example, Il10−/− mice develop chronic colitis which results from the absence of suppression of MyD88-dependent commensal-induced inflammation by IL-10." (PMID 26981546, 2016). "This critical role of B cell-derived IL-10 was first demonstrated in a murine model of chronic colitis, in which the absence of Breg cells has been identified as the probable cause of the disease." (PMID 26244559, 2015). "This emphasizes that GelE activity of E. faecalis in vivo is not affected by the deletion of epaB or lgt and suggests that GelE-mediated cleavage of E-cadherin is not crucial for the induction of chronic colitis in IL-10-/- mice." (PMID 26067254, 2015). "At this time point, Il10−/− and DKO mice have severe chronic colitis, while Tnf−/− and mast cell-deficient sash mice do not." (PMID 20808919, 2010). "In addition, our study revealed a negative correlation between the levels of β-hydroxybutyrate in rats with chronic colitis and proinflammatory cytokines such as TNF-α, IL-6, IL-1β, and IL-18, with a strong tendency towards a positive correlation with IL-10 levels." (PMID 37513865, 2023). "Il33 was not increased in Il10−/− mice with chronic colitis compared to WT mice." (PMID 33953267, 2021). "Hence, C. coli translocated in single cases from the intestinal tract to extra-intestinal, but not to systemic compartments upon infection of IL-10-/- mice with pre-existing chronic colitis." (PMID 32664563, 2020). "Interestingly, a 6-week intestinal MDR Psae carriage by IL-10−/− with chronic colitis did not alter the microbiota within the inflamed colon lumen." (PMID 29704005, 2018). "In chronic colitis (63 days), MP did not affect the TNF-α, IL-β, IL-6 and IL-10 blood levels, which is consistent with our data." (PMID 40863977, 2025). "The frequency of IL-10+ Th17 cells was increased significantly and there was no significant upregulation of IFN-γ+ Th17 cells in mice model of chronic colitis, resulting in the decrease of IFN-γ+ Th17 cells/IL-10+ Th17 cells." (PMID 34956391, 2021).
Chronic colitis (continued). "The level of IL-10 with anti-CD3 and anti-CD28 mAb stimulation and without any stimulation was significantly increased in the IL-33-treated chronic colitis group compared with the control group." (PMID 30539029, 2018). "Since piroxicam was not effective in enhancing the development of sustained chronic colitis to a level which could be detected with USMI, we also tested the feasibility of TNBS at inducing sustained chronic colitis in IL-10-/- mice." (PMID 31534535, 2019). "The gradual recruitment and activation of immune cells to the intestines in chronic colitis, as well as the lack of TLR4 and IL-10 signaling, suggests activation of immune pathways and secretion of cytokines that might differ from acute colitis." (PMID 20976045, 2010).
pulmonary fibrosis (125 papers, 2005 to 2026). Chronic progressive interstitial lung disorder characterized by the replacement of the lung tissue by connective tissue, leading to progressive dyspnea, respiratory failure, or right heart failure. "Conversely, IL-10 deficiency accelerates the progression of bleomycin-induced pulmonary fibrosis in mice." (PMID 41312367, 2025). "Sustained expression of IL-10 in lung tissue via an adeno-associated virus vector can ameliorate BLM-induced pulmonary fibrosis." (PMID 40438789, 2025). "The differences in serum BAFF, IL-17, and IL-10 were compared among patients with idiopathic pulmonary fibrosis (IPF), IPAF, ILD associated with CTD (CTD-ILD), and healthy controls." (PMID 38465342, 2024). "Mice with a B cell-specific deficiency in IL-6 exhibited attenuation of their skin and lung fibrosis, whereas those with a B cell-specific deficiency in IL-10 had severe skin and lung fibrosis." (PMID 35860745, 2022). "A protective role of Bregs was supported by the evidence that B cell-specific IL-10-deficient mice exhibited significantly increased dermal thickness and exacerbated lung fibrosis in a bleomycin-induced scleroderma model." (PMID 32708044, 2020). "Mice with a B cell-specific deficiency in the IL-10 production showed a more severe skin and lung fibrosis, compared to mice with sustained IL-10 production by B cells." (PMID 31036055, 2019). "On the other hand, along with its known anti-inflammatory effects, long-term overexpression of IL-10 has been associated with lung fibrosis." (PMID 25303100, 2014). "First, alveolar macrophages, strongly implicated in the pathogenesis of lung fibrosis induced by silica particles, were identified as the main cellular source of IL-10 in mice." (PMID 16212659, 2005). "IL-10 is also an antifibrotic agent for pulmonary fibrosis caused by viruses." (PMID 40508859, 2025). "Amongst them, IL‐1β, IL‐10, and IL‐13 are associated with pulmonary fibrosis." (PMID 38952051, 2024). "Conversely, IL-10 overexpression has been linked to the development of pulmonary fibrosis in vivo." (PMID 29690905, 2018). "However, transgenic overexpression of IL-10 can cause lung fibrosis, suggesting potential harmful effects of excess IL-10 beyond its beneficial immunoregulatory role." (PMID 28835901, 2017). "Overexpression of IL-10 has also been linked to the development of pulmonary fibrosis in vivo." (PMID 26138704, 2015). "In light of these observations, the authors conclude that TIM-3-expressing macrophages exacerbate pulmonary fibrosis, probably due to increased production of profibrogenic markers of pulmonary fibrosis, IL-10 and TGF-β." (PMID 41596489, 2026). "In a bleomycin-induced mouse pulmonary fibrosis model, a hyaluronic acid–heparin hydrogel was used as a carrier for IL-10 (HH-10), and intranasal administration ensured its sustained release." (PMID 41312367, 2025). "It has been reported that Tregs depletion in lung fibrosis attenuates fibrosis, potentially relying on the indirect effects of IL-10 and TGF-β secreted by Tregs." (PMID 40247299, 2025). "In a bleomycin pulmonary fibrosis model, the platform enables durable and sustained delivery of IL-10 to alleviate hypoxemia and rescue lung architecture." (PMID 41356371, 2025). "IL-10, in turn, promotes the differentiation of M2 macrophages, which are known to contribute to lung fibrosis." (PMID 41375773, 2025). "The therapeutic relevance of IL10 has been demonstrated, and its hydrogel-based delivery improves bleomycin-induced lung fibrosis in mice." (PMID 40001601, 2025). "The combination of IL-10 with rapamycin has been shown to inhibit the progression of pulmonary fibrosis with greater efficiency." (PMID 41312367, 2025). "Administration of a TGFβ1-expressing plasmid increased Tregs producing TGFβ1 and IL-10, ameliorating pulmonary fibrosis in mice." (PMID 40247299, 2025).
pulmonary fibrosis (continued). "In models of ARDS, IL-10 and IL-1Ra delivery attenuated LPS-induced inflammatory cytokines and reprogrammed the immune landscape toward a reparative phenotype, while in pulmonary fibrosis, the same approach enhanced fibrotic resolution." (PMID 41356371, 2025). "IL-10 delivery can inhibit bleomycin-induced pulmonary fibrosis by suppressing the production of TGF-β1 from alveolar macrophages, lung fibroblasts, and myofibroblasts." (PMID 41312367, 2025). "In a mouse model of pulmonary fibrosis, intravenous injection of collagen-conjugated micelles carrying VWF-A3 fused IL-10 (A3-IL-10) significantly improved the degree of pulmonary fibrosis." (PMID 41312367, 2025). "Vesicles from Akkermansia muciniphila reduce IL-6 production and increase IL-10 secretion, thereby alleviating carbon tetrachloride-induced pulmonary fibrosis in mice." (PMID 41304154, 2025). "Overexpression of TIM-3 can induce macrophages to secrete more TGF-β1 and IL-10, aggravating the pathological changes in pulmonary fibrosis, and regulating the expression of TIM-3 can regulate the development of pulmonary fibrosis." (PMID 36825939, 2023). "Several previous studies have found that IL-10 can suppress the activity of fibroblasts and ameliorate pulmonary fibrosis." (PMID 36914565, 2023). "In particular, IL-10 exerts a potent immunomodulatory or anti-inflammatory effect and is an anti-fibrotic agent for pulmonary fibrosis." (PMID 36914565, 2023). "Another group described positive correlations between serum levels of IL-6 and IL-10 and mRSS, together with a positive relation between IL-10 and pulmonary fibrosis." (PMID 37833885, 2023). "These RNAs include IL-10 mRNA, miR-126 and miR-30b, which have been reported to protect lung fibrosis." (PMID 35665467, 2022). "In the SSc animal model, BAFF contributed to the skin and lung fibrosis by increasing IL-6-producing effector B-cells and suppressing IL-10-producing regulatory B-cells." (PMID 36590969, 2022). "Several in vivo and in vitro studies have demonstrated that IL-10 demonstrates anti-fibrotic function in pancreatic, liver, and bleomycin-induced lung fibrosis." (PMID 35493729, 2022). "Another article reported that lung fibrosis induced by IL-10 overexpression increased the expression of M2 macrophages in both BAL and whole lung tissues." (PMID 33604393, 2021). "Animal experiments have shown that pulmonary fibrosis worsens with over expression of IL-10 and development of fibrotic tissue is consistent with long-term sustained lung inflammation." (PMID 34868007, 2021). "Although IL-10 is commonly identified as an anti-inflammatory cytokine, mice with IL-10 overexpression developed lung fibrosis, with a dramatic upregulation of the numbers of M2 macrophages not only in the BALF but also in the whole lung tissue." (PMID 33670759, 2021). "Studies have shown that IL-8, IL-33, and IL-10 contribute to pulmonary fibrosis by targeting macrophages." (PMID 33723241, 2021). "By the way, findings from some studies have pointed that the elevations of the anti-inflammatory and immunosuppressive cytokines, such as IL-10, can attenuate the bleomycin-induced lung fibrosis." (PMID 33123311, 2020). "Further, depletion of Treg cells by anti-CD25 antibody in silica-induced lung fibrosis attenuates fibrosis, and this process is probably dependent on the indirect function of Treg-secreted IL-10 and TGFβ." (PMID 32676074, 2020). "For example, interleukin 10 (IL-10), an anti-inflammatory cytokine, was found to suppress the formation of lung fibrosis in vivo, yielding promising leads to eradicate fibrogenesis." (PMID 32899668, 2020). "Interleukin 10 level in the bronchoalveolar lavage (BAL) of patients with idiopathic pulmonary fibrosis (fibrotic with little inflammation) is higher than the patients with other ILD diseases with abundant inflammation." (PMID 31363402, 2019).